USP43 (ubiquitin specific peptidase 43)
Diseases named in the same sentence as USP43 in open-access papers (continued):
Sharing a sentence is not in itself a finding about the gene and the disease.
neutropenia (1 paper, 2017). A decrease in the number of neutrophils found in the blood. "A recent study reported the association of a missense variant in the ubiquitin gene USP43 with clozapine-associated neutropenia." (PMID 27400856, 2017).
non-small cell lung carcinoma (1 paper, 2024). A group of at least three distinct histological types of lung cancer, including non-small cell squamous cell carcinoma, adenocarcinoma, and large cell carcinoma. "A further investigation was undertaken to construct a radiation prediction model for early-stage or locally progressed non-small cell lung cancer (NSCLC) using six genes, including APOBEC3B, GOLM1, FAM117A, KCNQ1OT1, PCDHB2, and USP43." (PMID 38613804, 2024).
oral squamous cell carcinoma (1 paper, 2025). "Whilst no DUBs have previously been reported to regulate KIFC1, candidates from genome-wide screens for centrosome clustering regulators in Drosophila or oral squamous cell carcinoma, included orthologs of USP8 (CG5798) and USP43 (CG30421) and the pseudo-DUB USP54." (PMID 39789388, 2025).
tumor (12 papers, 2021 to 2025). "High USP43 expression in tumor tissues was substantially associated with surrounding organ infiltration and elevated CA19-9 levels." (PMID 37050932, 2023). "To validate the effect of USP43 on the tumorigenic capacity of OC cells in vivo, we performed a subcutaneous xenograft tumor assay in nude mice." (PMID 40890129, 2025). "Platinum resistance is a major contributor to the poor prognosis of OC, and USP43 influences the sensitivity of tumor cells to platinum-based drugs." (PMID 40890129, 2025). "Reducing the expression of USP43 can inhibit the proliferation and migration of both epithelial and drug-resistant OC cells and suppress tumor growth in vivo." (PMID 40890129, 2025). "USP43 is a rarely reported member of the USP family and is associated with tumor proliferation and metastasis." (PMID 40890129, 2025). "USP43 knockdown significantly inhibited the tumorigenic capacity of OC cells, resulting in slower tumor growth and significantly lower tumor volume and weight than in the control group." (PMID 40890129, 2025). "USP43 expression was higher in tumor tissues of cisplatin-resistant patients than in those sensitive to cisplatin." (PMID 38087046, 2024). "qPCR analysis revealed that the mRNA expression level of USP43 in tumor tissues (T) was significantly higher than in adjacent normal tissues (NT) of EOC patients." (PMID 38087046, 2024). "In patients with LUSC, increased USP43 expression is substantially correlated with tumor invasiveness, including larger tumors and advanced TNM stages, and with a reduced overall survival rate." (PMID 38613804, 2024). "Using the TCGA database, the expression of USP43 was studied in 33 types of cancer in order to compare the expression of USP43 between tumor and normal tissues." (PMID 37050932, 2023). "In PDAC tumor tissues, the correlation between USP43 expression and clinicopathological characteristics, immune cell infiltration, and prognosis was investigated." (PMID 37050932, 2023). "In this study, our results suggested that the change of USP43 expression was closely related to the invasion, migration, proliferation, tumor stemness, and tumor stem cell spheroidizing ability of CRC cells." (PMID 33391437, 2021). "Crucially, we propose the therapeutic paradigm of rational combination therapy, demonstrating that USP43-high neoplasms exhibit enhanced vulnerability to synergistic tumoricidal efficacy when targeted with SLC7A11 inhibitors in concert with platinum-based agents like cisplatin." (PMID 40890129, 2025). "Although these investigations have delineated USP43’s regulatory roles in tumor proliferation, metastasis, and glycolytic reprogramming, its functional engagement with other cellular processes—particularly the modulation of cell death modalities—has yet to be systematically explored." (PMID 40890129, 2025). "Knockdown of USP43 inhibited tumor growth and enhanced cisplatin sensitivity of EOCin vivo." (PMID 38087046, 2024). "USP43 functions as a tumor promoter in various malignant cancers." (PMID 38087046, 2024). "Thus, we concluded that knockdown of USP43 inhibited tumor growth and enhanced cisplatin sensitivity of EOC in vivo." (PMID 38087046, 2024). "In vivo xenograft tumors, silencing USP43 slowed tumor growth and enhanced cisplatin sensitivity." (PMID 38087046, 2024). "Interestingly, compared with normal tissue, the USP43 expression was significantly higher in tumor PDAC (P < 0.001)." (PMID 37050932, 2023). "High USP43 expression was positively associated with surrounding organ infiltration (P = 0.044) and high CA19-9 level (P = 0.049) in tumor tissues, indicating that it may be a prognostic factor." (PMID 37050932, 2023). "The study delves into the tumor-promoting impact in EOC, showing that USP43 enhances the proliferation, invasion, and migration of EOC, and facilitates EOC cells to enter the cell cycle’s proliferation phase." (PMID 38613804, 2024).
tumor (continued). "A recent study reports that USP43 is significantly upregulated in PDAC, suggesting its potential role in influencing tumor formation by promoting the proliferation of the expression of USP43 in PDAC." (PMID 38613804, 2024). "A recent study demonstrates that USP43 is substantially upregulated in BLCA and that its expression increases with tumor grade." (PMID 38613804, 2024). "In this context, RNA-sequencing analysis of OS cells and mesenchymal stem cells differentiated or not differentiated into osteoblasts reveals increased expression of four USPs in OS tumor cells: USP6, USP27x, USP41 and USP43." (PMID 34571917, 2021). "Immunohistochemical results from the human protein atlas (HPA) database showed that the protein level of USP43 in malignant tumor tissues was also higher than that in normal ovarian tissues." (PMID 40890129, 2025). "In the present study, by comparing the expression of the 56 USPs described in the literature, in seven OS cell lines and in mesenchymal stem cells or osteoblasts, we identified four USPs: USP43, USP41, USP27x and USP6, with increased expression in OS tumor cell lines." (PMID 34571917, 2021).
cancer (9 papers, 2021 to 2025). A tumor composed of atypical neoplastic, often pleomorphic cells that invade other tissues. "Genes associated with USP43 in EOC primarily focus on controlling cancer advancement and histone deacetylation (HDAC)." (PMID 38613804, 2024). "This review aims to provide a comprehensive overview of the existing scientific evidence implicating USP43 in cancer development." (PMID 38613804, 2024). "It has been discovered that the USP43/NuRD complex inhibits the expression of numerous cancer-related genes, including the epidermal growth factor receptor (EGFR)." (PMID 38613804, 2024). "The prognostic significance of ubiquitin-specific protease 43 (USP43) across diverse cancer entities." (PMID 38613804, 2024). "Previous research discovered that USP43 acts as a promoter in various types of cancer, including EOC." (PMID 38613804, 2024). "According to a study, the cancer’s malignant characteristics are more pronounced in patients with high levels of USP43 in EOC." (PMID 38613804, 2024). "The study proposed an imbalance in the inhibitory relationship between USP43 and EGFR/PI3K/AKT as a potential cause of cancer growth." (PMID 38613804, 2024). "The protein level of ubiquitin-specific protease 43 (USP43) was a prognostic predictor in numerous cancers; however, its function in PDAC is limited." (PMID 37050932, 2023). "USP43 belongs to the DUBs family involved in cancer development and progression." (PMID 38613804, 2024). "USP43, or ubiquitin-specific peptidase 43, is a DUB that has been shown to play a role in cancer pathogenesis and potentially in antiviral innate immunity." (PMID 41472683, 2025). "USP43, USP52, JOSD1, UCHL5 and OTUB1 all reduced levels of the HIF-1α target CA9 in the secondary validation screen in two different non-cancer cell lines." (PMID 39009674, 2024). "Several DUBs, including USP10, USP18, USP22, USP43, and USP51 have been identified as key regulators of ZEB1 stability, thereby promoting proliferation, migration and invasion of cancer cells across different malignancies." (PMID 39736693, 2024). "Regarding the four USPs that we have shown increased expression in OS cells, USP27x and USP43 are involved in the control of EMT and thus metastatic progression in various cancers." (PMID 34571917, 2021). "We obtained a six-gene signature (APOBEC3B, GOLM1, FAM117A, KCNQ1OT1, PCDHB2, and USP43) with the ability to predict overall survival and progression-free survival (PFS), which could translate into a prediction of the response to the cancer treatment received." (PMID 35565183, 2022).
USP43 also shares sentences with these, for which no sentence is quoted: cervical cancer (1 paper); colon adenocarcinoma (1); esophageal carcinoma (1); nonsmall cell lung cancer (1); pancreatic adenocarcinoma (1); progressive supranuclear palsy (1); rectum adenocarcinoma (1).